BDNF (brain derived neurotrophic factor)
Diseases named in the same sentence as BDNF in open-access papers (continued):
Sharing a sentence is not in itself a finding about the gene and the disease.
Stroke (continued). "Here, we investigated whether BDNF and APOE genotype influence how stroke patients with stable motor function respond to a targeted protocol of upper-limb motor therapy poststroke." (PMID 27242654, 2016). "Neurotrophin analysis in the acute phase of stroke suggest that this process is most likely mediated by NT-3 and not by BDNF as previously thought for GA therapy in EAE." (PMID 25821957, 2015). "In conclusion, despite evidence of higher circulating BDNF levels and better outcome in rt-PA-treated than in non-treated stroke patients, our results do not support the use of serum BDNF as a biomarker of stroke outcome." (PMID 26469350, 2015). "Considering the neuroprotective and neurotrophic characteristics of BDNF, ALA treatment could be a feasible approach to reduce infarct size in stroke patients." (PMID 25889793, 2015). "In this context, the objective of our study was to compare serum BDNF levels in rt-PA-treated and non-treated stroke patients and to investigate mechanisms involved in potential difference." (PMID 26469350, 2015). "Serum BDNF levels and t-PA/plasmin activity were measured at hospital admission and at up to 90 days in stroke patients receiving (n = 24) or not (n = 14) rt-PA perfusion." (PMID 26469350, 2015). "Our study revealed higher serum BDNF levels in the acute period following hospital admission (from day 1 to day 7) and better neurological recovery in rt-PA-treated than in non-treated stroke patients." (PMID 26469350, 2015). "Engraftment of CPs in adult stroke models reduced infarct size and improved neurological function, in part via secretion of glial cell line-derived neurotrophic factor (GDNF), brain-derived neurotrophic factor (BDNF), and nerve growth factor (NGF)." (PMID 25426016, 2014). "Notably, we previously reported a correlation between BDNF levels (ELISA tests) and GFAP expression (a marker of astrocytes activation) in stroke rats." (PMID 22962604, 2012). "There were no interactive effects of BDNF genotype and methylation percentages on 2 week or 1 year stroke outcomes in the multivariate logistic regression models." (PMID 23240009, 2012). "Whereas plasma and serum BDNF levels were not changed by stroke, stroke induced an increase in brain BDNF levels at 4 h and 24 h post-embolization, which was not correlated with stroke severity." (PMID 22195050, 2011). "The results report an increase in brain BDNF levels at 4 and 24 h after stroke onset, which, however, was not accompanied by parallel changes in plasma or serum." (PMID 22195050, 2011). "Individual plasma BDNF levels did not correlate with brain levels at any time point after stroke but a positive correlation (r = 0.67) was observed between individual plasma BDNF levels and stroke severity at 4 h post-embolization." (PMID 22195050, 2011). "Stroke did not modify serum BDNF levels, and individual serum BDNF levels did not correlate with stroke severity at any time point after stroke." (PMID 22195050, 2011). "Our results revealed that stroke did not significantly change plasma BDNF levels when stroke severity was not taken into account." (PMID 22195050, 2011). "The mechanisms by which plasma BDNF levels at 4 h post-embolization are related to stroke severity have not been investigated here." (PMID 22195050, 2011). "Similarly, in the chronic phase, while reduced BDNF levels do not correlate strongly with the Stroke Specific Quality of Life Scale (SS-QOL), they remain a key indicator of global recovery potential." (PMID 41598337, 2026). "The group of MCAO/R mice with Saline or BDNF plasmids alone could not even survive beyond day 5 at post-stroke." (PMID 41328343, 2026). "However, a 12-week clinical trial involving moderate-intensity aerobic exercise found that it did not increase serum BDNF levels post-stroke (P = 0.1)." (PMID 40256392, 2025).
Stroke (continued). "In addition, the HITT 3-week-ahead intervention appeared to promote BDNF expression and delivery in brain and plasma via the PGC-1α pathway after cerebral ischaemia, which may positively affect mobility in stroke patients." (PMID 40837062, 2025). "Recent breakthroughs identify angiogenesis as a “master regulator” of post-stroke recovery through dual mechanisms: a)Re-establishing cerebral perfusion via neovascularization; b) Supporting neurogenesis through VEGF, brain-derived neurotrophic factor (BDNF) cross-talk." (PMID 40606624, 2025). "Finally, it is important to acknowledge that BDNF is not the only mediator of stroke recovery that can potentially be upregulated by CE." (PMID 40462267, 2025). "The benefits of S1R agonism following stroke are not limited to motor recovery but also suggest cognitive improvement in post-stroke models when treated with the S1R agonists ulinastatin, oxeladin, and PRE-084 by rescuing BDNF through the NR2A-CaMKIV-TORC1 pathway." (PMID 40564128, 2025). "Furthermore, hypercapnic hypoxia led to increases in VEGF and BDNF expression within the stroke core, but not in the peri-infarct region." (PMID 41465442, 2025). "Boosting astrocytic BDNF release by administration of galectin‐1 led to significant improvement in functional recovery in an ischaemic rat model, and selegiline administration, proposed to increase NGF and FGF, led to modest improvement in one primary endpoint in a phase II stroke trial." (PMID 37702572, 2024). "Stroke induced a 61% increase of p-CREB expressions in the combined CD11b+/CD45+ microglia/macrophage populations in the WT IL compared to their non-stroke CL hemispheres, and a 2.07-fold increase of BDNF expressions via intracellular staining within these microglia/macrophages post-stroke." (PMID 38509618, 2024). "The secondary outcomes are the National Institute of Health Stroke Scale (NIHSS), Brunnstrom staging (BS), modified Ashworth scale (MAS), Modified Barthel Index (MBI), central motor conduction time (CMCT), precursor proteins of mature BDNF (proBDNF), and matrix metalloproteinase-9 (MMP-9) levels." (PMID 37735708, 2023). "BDNF levels were not dependent on the stroke size (p = 0.81, Kruskal-Wallis test, GraphPad Prism)." (PMID 35756121, 2022). "The lower levels of BDNF and EGF found in the stroke patients compared to the healthy controls cannot with certainty be ascribed to stroke per se; the stroke patients could in theory have lower levels of these growth factors independently of the stroke." (PMID 35756121, 2022). "Moreover, the levels of BDNF and activities of SOD are reduced in stroke animals." (PMID 35656440, 2022). "In addition, various neurotrophic factors secreted by astrocytes, such as nerve growth factor (NGF), brain-derived growth factor (BDNF), erythropoietin (EPO), vascular endothelial growth factor (VEGF), and glial derived neurotrophic factor (GDNF), are increased after stroke." (PMID 36159395, 2022). "So far no BDNF-increasing therapy has reached clinical use in stroke patients." (PMID 35756121, 2022). "Finally, it was found that circulating BDNF levels after stroke does not reflect BDNF levels during the stroke and that there is a correlation between severe stroke and high plasma BDNF levels during the acute phase." (PMID 35194435, 2021). "Thus, despite observing improvement in the scores of language performance, BDNF is not solely responsible for such improvement in language recovery after stroke." (PMID 34367374, 2021). "Stanne reported that BDNF levels measured during the acute stroke phase may not be correlated with early functional recovery (3 months post-stroke), but with late functional recovery (2 and 7 years post-stroke)." (PMID 33809965, 2021).
Stroke (continued). "Under pathological conditions in rodent models like after cerebral ischemia and stroke, WBV may also promote the expression of different neurotrophic factors and neurogenesis-related markers such as brain-derived neurotrophic factor (BDNF), insulin-like growth factor (IGF1), and doublecortin (DCX)." (PMID 35126091, 2021). "This suggests that serum BDNF levels at a specific phase of stroke may not be a particularly reliable predictor of later PSD development, and also helps to clarify why the reviewed studies yield apparently contradictory results." (PMID 34141514, 2021). "The BDNF cut-off point in post-stroke disability or recovery has not been clearly established." (PMID 33920472, 2021). "Another factors identified after stroke and which might directly affect NSC proliferation are, among others, fibroblast growth factor-2 (FGF-2), insulin-like growth factor-1 (IGF-1) and brain-derived neurotrophic factor (BDNF)." (PMID 33834025, 2021). "Similarly, neither the combined treatment of TP and CSF1R inhibitor in cerebral ischemia nor its relationship to BDNF/autophagic pathways in the stroke model has been explored." (PMID 33192177, 2020). "No impact of pathogenetical types of stroke on BDNF level was found." (PMID 33343231, 2020). "However, in this study, stroke severity and cognitive function before standard rehabilitation therapy were associated with MMP-9, not serum mature BDNF." (PMID 30322026, 2018). "Accordingly, it may not be surprising that the results of non-aerobic training studies (functional training) post-stroke and its effects on BDNF concentrations are inconsistent." (PMID 30210424, 2018). "Because of the crucial role of BDNF participates in the formation of appropriate synaptic connections in the brain, it seems that ELF-EMF may serve as a therapeutic treatment to improve the neuroplasticity after stroke." (PMID 30319398, 2018). "Particularly, we could not consider the relationship between serum BDNF levels and various functional impairments such as motor and cognition in stroke patients." (PMID 30322026, 2018). "The results of the current systematic review highlight that aerobic exercise can promote changes in central BDNF concentrations in animal models of stroke, while BDNF responses following non-aerobic exercises, such as reaching training and CIMT, are still controversial." (PMID 30210424, 2018). "In general terms, aerobic exercise training appears to promote changes in central BDNF concentrations post-experimental stroke in animals, while central BDNF responses following non-aerobic exercise training in the animal model of stroke are still controversial." (PMID 30210424, 2018). "However, the relationship between BDNF levels and depressive mood during the subacute stroke phase has not been well-studied." (PMID 30322026, 2018). "However, several studies have concluded that BDNF is not involved in post-stroke functional recovery." (PMID 28134845, 2017). "To investigate whether BDNF played an important role in the remyelination process after NAM treatment in ischemic stroke, we detected the expression of BDNF in the peri-infarct area 7 d and 14 d after stroke induction." (PMID 28656112, 2017). "The present study was designed to determine the molecular effects of rTMS on serum levels of mature BDNF, proBDNF and MMP-9 in poststroke patients with upper limb hemiparesis, and the relationship between serum biomarkers and functional evaluation of upper limb hemiparesis in patients after stroke." (PMID 27007747, 2016). "The present study which is the first to be designed to assess the impact of rt-PA treatment on circulating BDNF levels in stroke patients, revealed higher serum BDNF levels in rt-PA treated than in non-treated stroke patients at least from day 1 to 7 after stroke onset." (PMID 26469350, 2015).
Stroke (continued). "Moreover, neural crest-derived stem cells have been proved to secrete several active factors such as brain-derived neurotrophic factor (BDNF), basic fibroblast growth factor (bFGF), and Glial cell line-derived neurotrophic factor (GDNF) to enhance neurogenesis in brain after stroke." (PMID 25883981, 2015). "However, serum BDNF levels did not predict stroke outcome when the whole cohort of stroke patients was analyzed." (PMID 26469350, 2015). "Moreover, this phenotype was not altered by stroke since, in both sham and stroked rats, the predominant proportion (∼75%) of BDNF-producing cells were also AT2R-positive." (PMID 24752645, 2014). "Indeed, brain delivery of exogenous neurotrophic factors, such as the neurotrophin nerve growth factor (NGF) and brain-derived neurotrophic factor (BDNF), can reduce infarct volumes by 60–90% with near total restoration of behavioral function in experimental stroke models." (PMID 24818146, 2014). "Thus, whereas stroke increased brain BDNF levels at 4 h and 24 h, it did not induce significant changes in plasma or serum." (PMID 22195050, 2011). "Whereas plasma BDNF is taken up by platelets, the elevation of plasma BDNF levels at 4 h post-embolization did not lead to an increase in platelet BDNF content as evidenced by the lack of change of BDNF levels in serum after stroke." (PMID 22195050, 2011). "Assuming that circulating BDNF levels do not reflect levels present in the brain after stroke, some clinical data may need to be reinterpreted." (PMID 22195050, 2011). "This may because that BDNF antibody only blocked the activity of BDNF and may not suppressed the expression of local BDNF in brain after stroke." (PMID 21490702, 2010). "We also found that BDNF antibody may not change the expression of BDNF in brain tissues after stroke." (PMID 21490702, 2010). "In addition, it could be interesting to take measurements of BDNF, VEGF and lactate shortly after the exercise is finished to assess the duration of the effects in patients with stroke because it is estimated that the increase in BDNF from exercise only lasts for 20 min to 1 h in healthy subjects." (PMID 38610750, 2024). "A relationship between stroke severity and BDNF levels is commonly reported, but the lack of significant changes in our study in the face of clinical improvement may be due to the fact that only mild and moderate stroke patients were included in the study." (PMID 36969561, 2023). "In addition, BECs secrete neurotrophins, such as brain-derived neurotrophic factor (BDNF), insulin-like growth factor 1 (IGF1), and vascular endothelial growth factor (VEGF), to maintain normal brain homeostasis, suggesting that neurotrophic factors are a potent drug candidate for stroke therapy." (PMID 37458258, 2023). "In addition, EA may promote synaptic plasticity after stroke by protecting and improving synaptic ultrastructure in the rat ischemic cerebral cortex and increasing the expression of synaptophysin P38, GAP-43, NGF and BDNF." (PMID 36741282, 2023). "However, longitudinal studies investigating the correlation between BDNF levels and other biomarkers of neurodegeneration, as well as morphological and clinical changes, are needed to better understand the development of SDNG and recovery in the chronic phase after stroke." (PMID 37719764, 2023). "However, whether P2X7R has a clear regulatory effect on BDNF has not been clearly demonstrated in the area of stroke improvement." (PMID 35821455, 2023). "The stroke patients participating in the present study were relatively homogenous regarding the Barthel ADL scores which may explain why we did not see a correlation between BDNF levels and Barthel ADL scores." (PMID 35756121, 2022). "It is possible that selective induction of BDNF in the striatum may enhance recovery in subcortical or striatal stroke, a common stroke subtype, but not have an effect in other stroke subtypes, such as in cortex or other brain areas in which PDE10A levels are low." (PMID 32378029, 2021).
Stroke (continued). "Since decreases in BDNF levels are correlated with negative outcomes after stroke, studying the exercise factors that induce BDNF signaling and assessing their neuroprotective abilities may allow us to identify novel endogenous therapeutic agents for stroke." (PMID 34108925, 2021). "Similarly, Wang and colleagues tested whether serum BDNF can be served as a stroke outcome predictor or not." (PMID 33809965, 2021). "Importantly, the level of BDNF does not differ between sex, age and the initial severity of stroke." (PMID 33920472, 2021). "Thus, in this case, BDNF concentrations in the early phase of stroke may not accurately predict the risks of PSD development." (PMID 34141514, 2021). "Although few studies have evaluated BDNF levels in patients with nontraumatic brain lesions, the lack of difference according to the etiology of brain injury in this study is in agreement with the observation of reduced serum BDNF levels in the acute phase of stroke." (PMID 32565776, 2020). "However, many studies later reported that MSCs could release trophic factors and other signaling molecules such as brain-derived neurotrophic factor (BDNF), vascular endothelial growth factors (VEGF), and transforming growth factor (TGF) β, contributing to the functional recovery following stroke." (PMID 31560696, 2019). "However, BDNF has never been measured in the postmortem brains of stroke patients, although a slight increase in circulating neurotrophin levels observed after stroke could mirror brain levels." (PMID 28134845, 2017). "However, given the absence of a correlation between neurological outcomes and serum BDNF levels, measuring BDNF levels in serum may not be useful to predict the recovery in stroke patients." (PMID 26469350, 2015). "Although our results on methylation status in genomic DNA isolated from leukocytes with longterm stroke outcomes have some prognostic value, it is not clear whether this would be the relevant tissue/cell type to infer BDNF expression of most importance for stroke." (PMID 23240009, 2012). "However, it is not known how BDNF methylation status influences BDNF secretion over time after stroke, and it is important to bear in mind that there were no significant genotype-methylation interactions and no direct associations between BDNF genotype and methylation percentages in our sample." (PMID 23240009, 2012). "Indeed, circulating BDNF levels before hospital admission are unknown in patients, and there are no studies on circulating BDNF levels in animal models of stroke." (PMID 22195050, 2011). "Therefore, our conclusion that circulating BDNF levels do not reflect brain BDNF levels in stroke patients could only concern patients lacking reperfusion." (PMID 22195050, 2011). "However, the fact that plasma but not brain BDNF correlated with stroke severity supports the hypothesis that the excess of BDNF found in plasma of rats with severe stroke do not originate from the brain." (PMID 22195050, 2011). "However, BDNF levels have never been measured in post-mortem brains of stroke patients." (PMID 22195050, 2011). "For instance, studies have shown that incorporating neurotrophic peptides like BDNF into MSC-EVs using non-destructive methods and administering them via intranasal delivery significantly enhances post-stroke neuroregeneration." (PMID 41280893, 2025). "Silymarin raised cortical TNFα, IL4, IL10, IGF1, BDNF, and CX3CL1 levels in the HFD group with stroke, while the striatum did not present relevant differences." (PMID 39624169, 2024). "There was no statistical significance between stroke characteristics and telomere length, NR3C1, TNF-α, BDNF, MTNR1A, or MTNR1B expression." (PMID 38802847, 2024). "On comparison, no changes in the BDNF serum levels were seen in patients without PSD between 7 days and 6 months after the stroke." (PMID 37895349, 2023).